CD4 (CD4 molecule)
Diseases named in the same sentence as CD4 in open-access papers (continued):
Sharing a sentence is not in itself a finding about the gene and the disease.
myeloma (continued). "Our study strengthens the suggestion that myeloma growth disrupts both the qualitative and quantitative expression of immune checkpoints in the PB CD4+ T cell subsets, which may complicate the clinical response to therapeutic checkpoint inhibitors." (PMID 34502204, 2021). "In a myeloma model, BMSCs promoted MM cells, likely by suppressing CD4+ T cells via the PD-L1−PD-1 pathway, indicating that the anti-PD-1 antibody may inhibit BMSC-induced MM cell growth." (PMID 32290052, 2020). "Similarly, TAMs isolated from tumors of a murine multiple myeloma model became activated when co-cultured with TCR transgenic CD4+ Th1 cells specific for the tumor antigen." (PMID 30853959, 2019). "The mean percentage of Treg cells (CD4+CD25highFoxP3+) within CD4+ cells was much higher in the PBMCs of multiple myeloma patients than in healthy subjects, and decreased substantially after the first cycle with lenalidomide and glucocorticoids, even if the decrease was not significant." (PMID 30845709, 2019). "The CM1 CD8 and CD4 subsets were also increased compared to myeloma and MGUS." (PMID 31462637, 2019). "An effect on CD4+ T-cells was also observed in multiple myeloma patients wherein treatment with DCs and cytokine-induced killer cells (CIK) combined with bortezomib and dexamethasone improved CD4+/CD8+ T-cell ratios compared to baseline and treatment with chemotherapy alone." (PMID 30568653, 2018). "Moreover, an increased expression of KLF6-SV1 mRNA and protein in at least CD4+ T cells from CLL patients compared to T cells from myeloma patients and normal healthy donors was noted." (PMID 29432497, 2018). "Both CD8 and CD4 T cell subsets were important for eradicating myeloma." (PMID 28642819, 2017). "In myeloma, BM resident DCs recruit CD4+ T cells and prime Th17 differentiation." (PMID 28848556, 2017). "Furthermore, while the PD-1+CD4+ and CD8+ T cell subsets each contained anti-myeloma reactivity, the combination of PD-1+CD4+ and CD8+ T cells provided the best anti-myeloma effect." (PMID 28642819, 2017). "The observation that myeloma-reactive PD-1+ CD4+ and CD8+ T cells secrete both IFN-γ and IL-10 suggests these cells may be at the crossroads of an immune switch from effector to tolerogenic." (PMID 28642819, 2017). "Furthermore, co-culture of primary myeloma cells with CD4+/CD25−/FOXP3− T cells induced increased amount of inducible Tregs (CD4+/CD25+/FOXP3+)." (PMID 28482851, 2017). "Because our assay measures proliferation at six days, we considered that myeloma patients may harbor CD4+ effectors which could proliferate at different kinetics than less antigen experienced CD4+ cells within healthy donors." (PMID 25992291, 2015). "The CD4+ T cell subset may play a critical role in the lenalidomide-mediated anti-myeloma immune response in vivo." (PMID 26447613, 2015). "Increasing these cells in patients, via vaccination, could evaluate the relevance of survivin specific CD4+ T cells in myeloma patients." (PMID 25992291, 2015). "Notably, an higher CD4+/CD8+ ratio at the of leukapheresis, as well as higher frequency of CD8+CD45RO-CD27+ T cells (i.e., early lineage CD8+ T cells) were the only factors associated with clinical response in these multiple myeloma patients." (PMID 36358694, 2022). "Briefly, using TCR-tg mice and ACT experiments in MOPC315 multiple myeloma, B-lymphoma, and B16 tumor models, the authors described a mechanism in which secreted tumor antigen is taken up by tumor-infiltrating macrophages and presented to CD4+ T cells on MHC-II molecules." (PMID 36159781, 2022). "However, PBMC responses were not enhanced during lenalidomide maintenance and CD4+ T-cell responses specific for the myeloma-associated antigen MAGE-C1 even tended to become lower." (PMID 29755666, 2018). "Therefore it is necessary to analyze whether there is a positive correlation between the number of CD4+ T cells and response to lenalidomide in myeloma patients." (PMID 26447613, 2015).
myeloma (continued). "Alternatively, the differentiation state of the survivin reactive CD4+ T cells we identified in myeloma patients could be unprimed naïve cells or antigen experienced memory cells, however the paucity of the cells preclude direct phenotypic evaluation of maturation markers." (PMID 25992291, 2015). "Finally, we verified that our LDA assay was able to detect naïve CD4+ T cell responses in myeloma patients (n = 2) and a cord blood donor unit by stimulating CD4+CD25-CD45RO- cells with autologous DCs loaded with a peptide pool derived from the Consensus B gag motifs of HIV." (PMID 25992291, 2015). "One such powerful application, for example, is that of gene expression profiles tumor specific CD4+ T cells in a mouse model of multiple myeloma, which could possibly capture tumor specific protein interaction network mechanism using the approach described here." (PMID 25309909, 2014). "Our data demonstrates some important characteristics of T cell response in newly diagnosed multiple myeloma patients: i) low baseline CD3+, CD4+, CD8+ T cells, and CD4/CD8 ratio." (PMID 40641743, 2025). "The mononuclear cells from AL amyloidosis patients had lower expression levels than the cells from myeloma patients for BDNF, calmodulin, phospho‐TBK1, and phospho‐ULK1 in CD4+ T cells and phospho‐GSK3β in monocytes, but higher levels of HO1 in monocytes." (PMID 40977494, 2025). "The added benefit of BITEs involves the upregulation of multiple T-cell compartments, both CD4+ and CD8+, leading not only to myeloma cell lysis but also differentiation of naïve T cells into memory T cells as well." (PMID 36826140, 2023). "Dendritic cell (DC) activation through IMiD-enhanced DC-antigen presentation increases activation of CD4+/CD8+ T cells which promotes immune surveillance and an anti-myeloma profile." (PMID 36826140, 2023). "Reported immune alterations in multiple myeloma include defects in T cell function, a reduction of peripheral CD4+ and CD8+ T cells, abnormal Th1/Th2 ratio, a decrease in CD4/CD8 T cell ratio and a reduction in NKT cells." (PMID 37187728, 2023). "In this study, CD3+CD4+ and CD4+/CD8+ ratios were significantly reduced, and CD3+CD8+ was increased in patients with multiple myeloma at the initial and progressive stages, which was consistent with the previous reports." (PMID 35342422, 2022). "In 57 patients with multiple myeloma, our results showed that the proportion of CD3+CD4+ cells and CD4+/CD8+ significantly decreased in peripheral blood compared with healthy controls." (PMID 35342422, 2022). "In a phase 1 trial evaluating this DC/myeloma fusion vaccine, vaccination was well tolerated and resulted in expansion of CD4 and CD8 myeloma-reactive T cells and disease stabilization in the majority of patients." (PMID 36389674, 2022). "Our research data indicate that there are abnormalities of CD3+CD4+, CD3+CD8+, CD3−CD19+, and CD16+CD56+ cells in patients with multiple myeloma." (PMID 35342422, 2022). "6-FPHMA inhibited P2X7-mediated dye uptake into human T cells, including CD4+ and CD8+ T cell subsets, and human RPMI8226 multiple myeloma cells." (PMID 36139148, 2022). "IL-15 mDCs also showed higher stimulatory capacity regarding autologous T cells, a higher proportion of CD44+ and IFN-γ+ in CD4+ and CD8+ T cells, and higher cytotoxicity of T cells against cancer cell lines and patient autologous primary myeloma cells." (PMID 35413499, 2022). "HD volunteers showed increased T-cell counts, higher CD4/CD8 ratio, and expanded naïve T-cell population compared with patients with multiple myeloma." (PMID 36874402, 2022). "A prior study reported that DCZ0415 significantly increases the infiltration of CD3, CD4 and CD8 in a myeloma model." (PMID 35194944, 2022). "In a subsequent phase 2 trial following autologous SCT, vaccination significantly increased CD4 and CD8 myeloma-specific T cells, with a CR rate of 47% and a 2-year PFS of 57%." (PMID 36389674, 2022).
myeloma (continued). "In order to further analyze the possible mechanism, we measured the proportion of CD3+CD4+, CD3+CD8+, CD3−CD19+, and CD16+CD56+ cells in peripheral blood of patients with multiple myeloma." (PMID 35342422, 2022). "To further validate the TETact system, we attempted to activate CD4 in additional cell lines – 3T3 fibroblasts, MPC11 myeloma and J558L plasmacytoma." (PMID 36151095, 2022). "Regulatory CD4+ T cells (Treg) and cytotoxic CD8+ T cells have emerged as the dominant effectors in host myeloma control in syngeneic transplantable murine myeloma models underpinning autologous graft versus myeloma as an important process in disease control." (PMID 33708212, 2021). "For instance, low CD4 + T cell counts and CD4/CD8 ratio were independent unfavorable prognostic predictors for patients with multiple myeloma, waldenstrom macroglobulinemia and mantle cell lymphoma patients at diagnosis." (PMID 34930155, 2021). "The literature reported that numbers of cicrculating total CD3+, CD4+, and CD8+ T cell significantly raised with targeting CD38 treatment in multiple myeloma patients." (PMID 34211854, 2021). "Despite the role of other immune cells, CD4+ regulatory T cells (Treg) and cytotoxic CD8+ T cells have emerged as the dominant effectors of host control of the myeloma clone." (PMID 33708212, 2021). "While this effect was dependent on both CD8 and CD4 T cells, CD8 T cells were the cognate effectors of myeloma-specific immunity." (PMID 33777050, 2021). "PD1 expression in CD4+ and CD8+ T cells is increased after treatment in multiple myeloma patients with persistent disease." (PMID 33287189, 2020). "A Dkk1 vaccination study in a murine model of myeloma showed higher CD4+ and CD8+ T-cell immune activity and provided a strong rationale for using Dkk1 as a myeloma immunotherapeutic target." (PMID 33126517, 2020). "An in vivo murine myeloma model showed that low-dose irradiation followed by anti-PD-1 treatment prolonged survival with increased tumor-specific CD8+ T cells, in which both CD4+ and CD8+ T cells were necessary to eliminate MM cells." (PMID 32290052, 2020). "Flow cytometry showed an expansion of both CD8+ and CD4+ T cell populations and a significant increase in activated CD4+ and CD8+vβ (2, 3, 8.3)+ T cells, confirming their reactivity against myeloma target cells." (PMID 31727148, 2019). "CD4+CD45RA−FoxP3hi aTreg cells and CD4+CD28−FoxP3+ aging Treg-like cells were quantitatively impaired both in MGUS and newly diagnosed myeloma patients." (PMID 30479566, 2018). "The percentage of spleen PD-1+CD4+ and CD8+ T cells in naïve non-myeloma bearing mice is relatively low (~4–7%), as compared to moribund 5T33 bearing mice where 20–60% are PD-1+." (PMID 28642819, 2017). "Multiple myeloma-induced immune paresis is mainly attributed to the impairment of T-cell (CD4+, and CD8+) activation and proliferation, which is mediated by myeloma cell-induced production of transforming growth factor (TGFβ)." (PMID 28032590, 2017). "Blockade of this axis using an anti-PD-L1 Ab increases CD4+ T cell proliferation and CTL activity against human MM cells in vitro and is curative in a murine model of myeloma in combination with antagonists of the IAP (inhibitors of apoptosis) proteins." (PMID 28848556, 2017). "Some of these alterations were striking with the proportion of bone marrow CD4 and CD8+ T cells which expressed CCR4 being increased from 4.4% and 3% respectively in the control group to 20% and 12% in patients with myeloma." (PMID 28389623, 2017). "To complete our studies, we also tested inhibitory markers’ expression on CD4+ T cells from PB and BM and also CD8+ T cells from PB of treated myeloma patients." (PMID 27809856, 2016). "We have, for the first time, quantified the circulating CD4+CD25- precursor frequency against survivin and demonstrated this is lower in myeloma patients than healthy donors." (PMID 25992291, 2015).
myeloma (continued). "Our previous study and other studies have identified that human MDSCs from solid tumors or multiple myeloma can suppress anti-CD3-induced autologous or allogeneic T cell proliferation, including CD4+ and CD8+ T cells." (PMID 26497849, 2015). "We therefore examined CD4 and CD8 T cells for the expression of other checkpoint receptors over time in myeloma-bearing animals." (PMID 25614821, 2015). "In an MHC IINEG myeloma model, secretion of tumor-specific myeloma protein clearly facilitates priming of APC in lymph nodes and stimulation of naive CD4+ T cells that subsequently infiltrate the tumor site." (PMID 24782871, 2014). "The expansion of circulating CD4+ and CD8+ T cells reactive with autologous myeloma cells in 11 of 15 evaluable patients were detected." (PMID 22481968, 2012). "These Id-specific TCR transgenic mice are protected against transplanted myeloma, and the primary anti-tumor response is mediated by the Id-specific TCR transgenic CD4+ T cells." (PMID 23144743, 2012). "We have reported an expanded pool of CD4+CD25high Treg cells in patientswith chronic lymphatic leukemia (CLL), multiple myeloma (MM) as well as its premalignant precursor monoclonal gammopathy of undetermined significance (MGUS)." (PMID 21904560, 2011). "Both Vav and phospho‐cJun are strongly correlated with various phosphoantigens as well as with each other in CD4+ T cells from myeloma patients, but not in the cells from patients with AL amyloidosis." (PMID 40977494, 2025). "BDNF and phospho‐TBK1 were significantly correlated in CD4+ T cells from AL amyloidosis patients but not in myeloma patients." (PMID 40977494, 2025). "Excepting a higher frequency of CD4+IFN+ T cells in unstimulated samples in myeloma patients, there were no other differences regarding unstimulated and CEF-Peptides- stimulated samples in the two patient groups." (PMID 37187728, 2023). "CD4/CD8 ratio was variable in patients with newly diagnosed multiple myeloma (3.67 ± 1.27) but not significantly different from HDs (1.43 ± 0.1) or patients with early relapsed multiple myeloma (1.18 ± 0.2)." (PMID 36874402, 2022). "In the absence of myeloma cells, lenalidomide and pomalidomide induce CD4+ T cell secretion of IL-2 and indirect activation of Natural Killer (NK) cells." (PMID 33746969, 2021). "Thus, there is a critical need to further study CD8 and CD4 T cell function, phenotype, and myeloma-specific immunity within the BM TME of myeloma patients after ASCT in order to define the optimal timing for immunotherapy approaches." (PMID 33777050, 2021). "Our analysis revealed a distinct immune profile between MRD+ and MRD– patients, with the latter showing a more experienced adaptive immunity (i.e., CD4+ and CD8+ T cells) phenotype, probably indicative of competent immune surveillance keeping myeloma burden in repression." (PMID 33158030, 2020). "High levels of CD38 have been described on a subpopulation of peripheral CD4+CD25+CD127dim regulatory T cells, which are sensitive to therapeutic intervention with the CD38-specific monoclonal antibody daratumumab in individuals with multiple myeloma." (PMID 29881878, 2018). "Tumor-specific CD4 T cells became activated in the draining lymph nodes of myeloma tumors, but not in lymph nodes of the control tumors." (PMID 29032503, 2018). "The present results identify the molecular mechanisms underlying macrophage-mediated killing of tumor cells in the context of a CD4+ Th1 cell response against MHC class II negative multiple myeloma cells." (PMID 30083157, 2018). "Recent data from our lab suggests that MHC II-deficient myeloma cells can be eliminated by a combinatorial regimen of CD4+ ACT and sub-lethal irradiation in the setting of established, disseminated myeloma within the bone marrow, although the effector cells in this setting have not been identified." (PMID 27626487, 2016).
myeloma (continued). "Our results demonstrate that ablation of the relevant MHC II (I-Ed) in multiple myeloma cells (MOPC315) does not hinder rejection by tumor-specific CD4+ T cells." (PMID 27626487, 2016). "These in vivo results demonstrated that CD4+ T cells but not CD8+ or B cells are crucial in the lenalidomide-mediated anti-myeloma immune response in vivo." (PMID 26447613, 2015). "In order to better understand the anti-tumor immune response to survivin, and optimize vaccination strategies, we characterized the spontaneous CD4+CD25- T cell response against survivin in healthy donors and myeloma patients using survivin derived peptide pools." (PMID 25992291, 2015). "Furthermore, increased percentages of activated CD4, and even more so activated CD8 T cells, confirmed T-cell reactivity against myeloma cells and Balb/cJ cells among Allo-MM splenocytes." (PMID 25415267, 2014). "We treated with AZA to try to alter the methylation state of 3 cell systems from different GR-positive, GC-resistant human hematological malignancies: acute lymphoblastic leukemias Molt-4 (T-cell), and CEM clone C1-15 (CD4+/CD8+) and the multiple myeloma (B-cell) line RPMI 8226." (PMID 24795534, 2014). "However, in our in vitro system, myeloma tumour cells generate and expand tTReg cells in an APC-free manner, that is directly inducing CD4+CD25- T-cells." (PMID 22666318, 2012). "Additionally, BDNF and phospho‐TBK1 were tightly correlated in the CD4+ T cells from the AL amyloidosis patients but not in the cells from patients with myeloma." (PMID 40977494, 2025). "In another study, daratumumab plus lenalidomide and dexamethasone (D-Rd) downregulated CD38 expression in multiple myeloma (MM) patients compared to Rd, especially in NK cells, B cells, basophils, monocytes, and CD4+ T cells, with no significant change in CD8+ T cells." (PMID 40821821, 2025). "Consequently, we included it in logistic regression models and discovered its inclusion markedly improved the predictive power of BDNF expression in CD4+ T cells to distinguish between AL amyloidosis patients and myeloma patients without amyloid deposits." (PMID 40977494, 2025). "This includes that patient 114 with myeloma had no B‐cell deficiency or reported vaccinations between visits; however, they exhibited higher N‐specific antibodies, Omicron neutralization, and non‐spike AIM + CD4 T‐cells at their last visit." (PMID 39659018, 2024). "The composition of endogenous T cells used in manufacturing the CAR product, including the CD4:CD8 ratio and presence of central memory and stem cell memory T cells, has been shown to affect CAR T expansion, anti-tumor activity, and clinical response in myeloma and other B cell malignancies." (PMID 36389674, 2022). "Analysis of CD4 T cells showed a significantly higher proportion of naïve/stem cell memory (SCM) phenotype in HDs (30.8 ± 7.7%) compared with newly diagnosed multiple myeloma (11.1 ± 2.4%, P < 0.05) or patients with relapsed multiple myeloma (6.0 ± 1.5%, P < 0.05)." (PMID 36874402, 2022). "Furthermore, this study showed that the treatment of immunocompetent myeloma models with DCZ0415 increases the numbers of immune cells (CD3, CD4 and CD8) and inhibits nuclear factor kappa B (NF‐κB) activity, suggesting the immunotherapeutic value of inhibiting TRIP13." (PMID 35194944, 2022). "Also, relative and absolute counts of PB CD4+FOXP3+ T cells did not correlate with the relative count of BM myeloma PCs: rS=0.17, p=0.35, and rS=0.11, p=0.55, respectively." (PMID 29930767, 2018). "The spontaneous CD4+ response against survivin in myeloma patients has not been characterized, and must be understood to optimize vaccine strategies against aggressive survivin expressing myeloma." (PMID 25992291, 2015).